ZNF771 (zinc finger protein 771)
Description:
May be involved in transcriptional regulation.
Synonyms: DSC43
Tractability: PROTAC: UniProt records ubiquitination sites on it; ubiquitination databases record sites on it; its protein half-life has been measured.
Gene: Protein-coding gene on chromosome 16 (30,407,143 to 30,431,108, forward strand). Ensembl gene ENSG00000179965.
Subcellular location: Nucleus
Subcellular location (Human Protein Atlas): Nucleoli; Nucleoplasm
Pathways (Reactome):
Gene expression (Transcription): Generic Transcription Pathway
Gene Ontology:
Molecular function: sequence-specific double-stranded DNA binding; DNA-binding transcription factor activity, RNA polymerase II-specific
Biological process: regulation of transcription by RNA polymerase II
Cellular component: nucleolus; nucleoplasm; nucleus
Genetic constraint (gnomAD): Loss-of-function variants: 10 observed, 11.57 expected, observed/expected ratio (o/e) 0.86, 90% interval 0.53 to 1.46. The synonymous counts are far from expectation, so gnomAD's model fits this gene poorly and the ratio says little. Missense variants: 438 observed, 322.87 expected, observed/expected ratio (o/e) 1.36, 90% interval 1.25 to 1.47. Synonymous variants: 261 observed, 150.27 expected, observed/expected ratio (o/e) 1.74, 90% interval 1.57 to 1.91.
Homologues: Orthologues: chimpanzee ZNF771 (100% identical), macaque ZNF771 (99% identical), dog ZNF771 (97% identical), pig ZNF771 (97% identical), guinea pig ZNF771 (96% identical), mouse Zfp771 (96% identical), rat Zfp771 (95% identical). Paralogues in human: ZNF48 (44% identical), ZNF160 (40% identical), ZNF84 (39% identical), ZNF420 (39% identical), ZNF184 (38% identical), ZNF497 (37% identical), ZNF91 (37% identical), ZNF689 (36% identical), ZNF347 (36% identical), ZNF845 (36% identical), ZFP92 (35% identical), ZNF99 (35% identical), and 24 more.
Diseases named in the same sentence as ZNF771 in open-access papers:
ZNF771 is named in the same sentence as 2 diseases in open-access papers, as found by Europe PMC text mining. Sharing a sentence is not in itself a finding about the gene and the disease. The quoted sentences say what the papers report.
Obesity (1 paper, 2024). Accumulation of substantial excess body fat. "An epigenome-wide association study on obesity identified three notable loci: cg18181703 (SOCS3), cg04502490 (ZNF771), and cg02988947 (LIMD2)." (PMID 39498440, 2024).
metabolic disorders (1 paper, 2024). "ZNF771, one of the key feature genes identified in this research, offers valuable insights through bioinformatics analysis serving as a reference for future research focused on its role in metabolic disorders." (PMID 39498440, 2024).